MED1 (mediator complex subunit 1)
Description:
Component of the Mediator complex, a coactivator involved in the regulated transcription of nearly all RNA polymerase II-dependent genes. Mediator functions as a bridge to convey information from gene-specific regulatory proteins to the basal RNA polymerase II transcription machinery. Mediator is recruited to promoters by direct interactions with regulatory proteins and serves as a scaffold for the assembly of a functional preinitiation complex with RNA polymerase II and the general transcription factors. Acts as a coactivator for GATA1-mediated transcriptional activation during erythroid differentiation of K562 erythroleukemia cells.
Synonyms: PBP; Trap220; CRSP1; CRSP200; DRIP205; DRIP230; PPARBP; PPARGBP; RB18A; TRIP2
Tractability: Small molecule: a structure with a bound ligand is known. PROTAC: ubiquitination databases record sites on it; its protein half-life has been measured.
Gene: Protein-coding gene on chromosome 17 (39,404,285 to 39,451,272, reverse strand). Ensembl gene ENSG00000125686.
Subcellular location: Nucleus
Subcellular location (Human Protein Atlas): Nucleoplasm; Vesicles
Pathways (Reactome):
Circadian clock: BMAL1:CLOCK,NPAS2 activates circadian expression; Expression of BMAL (ARNTL), CLOCK, and NPAS2; RORA,B,C and NR1D1 (REV-ERBA) regulate gene expression
Gene expression (Transcription): Generic Transcription Pathway; MLL4 and MLL3 complexes regulate expression of PPARG target genes in adipogenesis and hepatic steatosis; Nuclear Receptor transcription pathway
Metabolism: Activation of gene expression by SREBF (SREBP); PPARA activates gene expression; Regulation of lipid metabolism by PPARalpha
Cellular responses to stimuli: Cytoprotection by HMOX1; Heme signaling
Developmental Biology: Transcriptional regulation of white adipocyte differentiation
Disease: RSV-host interactions
Organelle biogenesis and maintenance: Transcriptional activation of mitochondrial biogenesis
Signal Transduction: Estrogen-dependent gene expression
Gene Ontology:
Molecular function: chromatin binding; DNA-binding transcription factor binding; LBD domain binding; nuclear estrogen receptor binding; nuclear receptor binding; nuclear retinoic acid receptor binding; nuclear thyroid hormone receptor binding; nuclear vitamin D receptor binding; peroxisome proliferator activated receptor binding; protein binding; transcription coactivator activity; transcription coactivator binding; transcription coregulator activity; transcription corepressor activity; chromatin DNA binding; DNA binding; general transcription initiation factor binding; histone acetyltransferase binding; promoter-specific chromatin binding; protein-containing complex binding; RNA polymerase II cis-regulatory region sequence-specific DNA binding; RNA polymerase II-specific DNA-binding transcription factor binding; ubiquitin protein ligase activity
Biological process: androgen biosynthetic process; cell morphogenesis; cellular response to epidermal growth factor stimulus; cellular response to steroid hormone stimulus; cellular response to thyroid hormone stimulus; fat cell differentiation; keratinocyte differentiation; negative regulation of keratinocyte proliferation; nuclear receptor-mediated steroid hormone signaling pathway; positive regulation of DNA-templated transcription; positive regulation of erythrocyte differentiation; positive regulation of gene expression; positive regulation of keratinocyte differentiation; positive regulation of transcription by RNA polymerase II; positive regulation of transcription initiation by RNA polymerase II; regulation of RNA biosynthetic process; thyroid hormone receptor signaling pathway; angiogenesis; erythrocyte development; lens development in camera-type eye; megakaryocyte development; mRNA transcription by RNA polymerase II; negative regulation of apoptotic process; negative regulation of neuron differentiation; negative regulation of transcription by RNA polymerase II; and 6 more
Cellular component: core mediator complex; mediator complex; membrane; nucleolus; nucleoplasm; nucleus; chromatin; protein-DNA complex; ubiquitin ligase complex
Genetic constraint (gnomAD): Loss-of-function variants: 10 observed, 98.85 expected, observed/expected ratio (o/e) 0.1, 90% interval 0.061 to 0.17. The upper end of that interval is the gene's LOEUF score, 0.17, which puts it in group 1 of 6, group 1 being the genes least tolerant of losing a copy. Missense variants: 1,378 observed, 1,823.4 expected, observed/expected ratio (o/e) 0.76, 90% interval 0.72 to 0.79. Synonymous variants: 598 observed, 665.69 expected, observed/expected ratio (o/e) 0.9, 90% interval 0.84 to 0.96.
Homologues: Orthologues: chimpanzee MED1 (99% identical), macaque MED1 (99% identical), dog MED1 (98% identical), rabbit MED1 (98% identical), pig MED1 (98% identical), guinea pig MED1 (96% identical), mouse Med1 (94% identical), rat Med1 (94% identical), tropical clawed frog med1 (74% identical), zebrafish med1 (61% identical), Drosophila melanogaster MED1 (21% identical).
Diseases named in the same sentence as MED1 in open-access papers:
MED1 is named in the same sentence as 87 diseases in open-access papers, as found by Europe PMC text mining. Sharing a sentence is not in itself a finding about the gene and the disease. The quoted sentences say what the papers report.
breast carcinoma (48 papers, 2006 to 2026). "We observed that a small RNA, miR-205, is inversely correlated with MED1 expression levels in breast cancer patients, with low levels of miR-205 and high levels of MED1 associated with poor survival." (PMID 39682180, 2024). "Overexpression of MED1 has been linked to tamoxifen resistance and worse survival outcomes in breast cancer patients." (PMID 37705755, 2023). "The first recognized carcinogenetic process with Mediator complex was the association between MED1 and breast cancer." (PMID 36229463, 2022). "The first known link between MED and cancer was the association of MED1 and BC in breast cancer tissues and cell lines." (PMID 35205279, 2022). "The results showed that MED1 LxxLL motif mutations can delay mammary tumor onset by an average of about 16 weeks when compared to normal controls." (PMID 35205279, 2022). "Breast cancer patients with estrogen receptor positive breast cancer showed a strong association between higher miR-205 expression and better overall survival in contrast to Med1 whose overexpression associated with poor survival." (PMID 34389732, 2021). "High expression of miR-205 and low expression of Med1 associated with better overall survival in breast cancer patients with estrogen receptor positive breast cancer." (PMID 34389732, 2021). "Next, we interrogated the association of miR-205, Med1 (PPARBP) and leptin with overall survival of breast cancer patients." (PMID 34389732, 2021). "We show that both MED1 and miR-191 promote cell proliferation and migration in breast cancer and induce the expression of several genes associated with these properties." (PMID 30087366, 2018). "The association between MED1 transcript levels and prognosis of breast cancer patients was examined using TCGA dataset with clinical annotations." (PMID 30087366, 2018). "Overall, the results strongly indicated that deregulation of MED1 affects the levels of several breast cancer associated miRNAs." (PMID 30087366, 2018). "Certain studies have reported that MED1 amplification or overexpression is significantly associated with poor outcomes in breast cancer patients treated with hormone therapy." (PMID 28045951, 2017). "MED1 alterations have been implicated in bladder and breast cancers and may be a potential target for treatment in endocrine-resistant breast cancer." (PMID 40981433, 2025). "However, the molecular mechanism underlying MED1 upregulation and activation in breast cancer treatment resistance remains elusive." (PMID 39682180, 2024). "Furthermore, like KDM5, MED1 has been implicated as a transcriptional coactivator that mediates breast cancer metastasis and treatment resistance." (PMID 36803422, 2023). "Since Med1 is a transcriptional coactivator, we queried whether obesity-associated upregulated-genes in breast cancer are transcriptional targets for Med1." (PMID 34389732, 2021). "Indeed, a strong association between higher Med1 expression and poor overall survival was observed in breast cancer patients with estrogen receptor positive breast cancer." (PMID 34389732, 2021). "Importantly, loss of MED1 resulted in a severe abrogation of ER target gene expression in in vitro transcription assays, and estrogen-dependent endogenous gene transcription and growth of breast cancer cells." (PMID 35800368, 2022). "MED1 is a tissue-specific co-activator of the estrogen receptor that mediates breast cancer metastasis and treatment resistance and when targeted in model systems, results in reduced growth and metastasis of breast cancer xenografts." (PMID 40981433, 2025). "Targeting MED1 has been employed in current strategies to overcome breast cancer treatment resistance." (PMID 40940746, 2025).
breast carcinoma (continued). "For example, the LXXLL motif peptides targeting ERα significantly suppressed the proliferation of breast cancer cells in vitro by interference with the MED1–ER binding interface." (PMID 40940746, 2025). "Clinically, MED1 expression is highly correlated with poor disease-free survival in breast cancer patients, and recent studies have reported an increased frequency of MED1 mutations in circulating tumor cells of patients after treatment." (PMID 41465117, 2025). "MED1’s involvement in estrogen resistance mechanisms has been demonstrated, where silencing MED1 sensitizes breast cancer cells to pure anti-estrogen fulvestrant both in vitro and in vivo." (PMID 41139924, 2025). "MED1 is overexpressed in over 50% of human breast cancer cases and co-amplifies with another critical breast cancer gene, the HER2 tyrosine kinase receptor." (PMID 41465117, 2025). "Specifically, the most prevalent kinase fusion genes differed by subtype: MED1::CDK12 in HER2+ breast cancer, PTK2::AGO2 in TNBC, and KAT6B::ADK in HR+/HER2‒ breast cancer." (PMID 41213951, 2025). "Background/Objectives: Estrogen receptor-α coactivator MED1 is overexpressed in 40–60% of human breast cancers, and its high expression correlates with poor disease-free survival of patients undergoing anti-estrogen therapy." (PMID 39682180, 2024). "Med1 protein expression was investigated by deubiquitinating enzymes (DUBs) overexpression in breast cancer cell lines." (PMID 38708315, 2024). "Together, the data support the significance of miR205/MED1 axis in regulating the tamoxifen resistance of human breast cancer cells." (PMID 39682180, 2024). "Our recent studies have further demonstrated that MED1 plays a critical role in tamoxifen resistance by direct crosstalk with the receptor tyrosine kinase HER2 signaling pathway in human breast cancer cells." (PMID 39682180, 2024). "MED1 targeting and its impact on therapy resistance was evaluated in control and tamoxifen-resistant breast cancer cell lines by miR-205 overexpression and inhibition." (PMID 39682180, 2024). "Significantly, the re-expression of miR-205 in vivo in orthotopic xenograft mouse models represses the expression of MED1 and confers sensitivity to otherwise tamoxifen-resistant breast cancer cells." (PMID 39682180, 2024). "To further examine the potential relevance of miR-205 and MED1 expression in human breast cancer patient samples, we analyzed a breast cancer patient dataset from the NCBI GEO database (GSE22220)." (PMID 39682180, 2024). "Together, these data suggest the possible regulation of MED1 by miR-205 in mediating disease relapse and tamoxifen resistance in breast cancer." (PMID 39682180, 2024). "This study investigates how MED1 is overexpressed and overactive in breast cancer and contributes to treatment resistance." (PMID 39682180, 2024). "An inverse correlation of miR-205 and MED1 was observed in breast cancer patients with high MED1/low miR-205, indicative of poor prognosis in long-term anti-estrogen treatment." (PMID 39682180, 2024). "We have previously reported that MED1, a key ER transcription coactivator, is overexpressed in about half of breast cancer and plays important roles in ERα-mediated transcription and tamoxifen resistance." (PMID 39682180, 2024). "Taken together, these results support that miR-205 can directly regulate the expression of MED1 through its 3′-UTR in breast cancer cells." (PMID 39682180, 2024). "We have demonstrated the role of miR-205 in regulating the tamoxifen resistance of breast cancer cells through MED1 in vitro in our above studies." (PMID 39682180, 2024). "MED1 has been reported to be overexpressed or amplified in a high percentage (40–60%) of human primary breast cancer." (PMID 39682180, 2024). "To investigate the molecular mechanisms controlling MED1 expression in breast cancer, we used three different microRNA target prediction programs (Pictar, TargetScan and miRanda) to screen for miRNAs that target MED1." (PMID 39682180, 2024).
breast carcinoma (continued). "The SE complex known as the component MED1 has been found to play an essential role in MM, melanoma, breast cancer, PCa, and glioma." (PMID 37501079, 2023). "YAP1 and TEAD4 can also recruit mediator complex subunit 1 (MED1), an important enhancer activating machinery, to facilitate breast cancer cell growth." (PMID 35883668, 2022). "Based on these findings, Zhang’s laboratory has developed a targeted approach to block MED1 specifically in anti-estrogen resistant breast cancers using an innovative RNA nanotechnology approach." (PMID 35800368, 2022). "Similar phenomena were also observed using human breast cancer cells and further supported the role of MED1 in HER2-treatment responses." (PMID 35800368, 2022). "MED1 overexpression was observed in 40–60% of breast cancers and positively correlated with the human epidermal growth factor receptor 2 (HER2) status." (PMID 36229463, 2022). "Initially, in breast cancer tissues and cell lines, MED1 amplification and overexpression were observed." (PMID 36229463, 2022). "When these MED1-LxxLL mutant knockin mice were further crossed with a HER2-driven mammary tumor model (MMTV-HER2), it was found that MED1 LxxLL mutations were able to significantly delay the tumor onset, growth and metastasis." (PMID 35800368, 2022). "Our recent study has confirmed the correlation of MED1 protein levels with HER2 status using human breast cancer tissue microarrays." (PMID 33691110, 2021). "Another possible mechanism is upregulation by key transcription factors, such as MED1 and c-Myc, in prostate cancer and breast cancer, respectively." (PMID 34858987, 2021). "pRNA-Her2apt-siMED1 effectively silenced MED1 in breast cancer cells, blocked tumor growth, and completely eradicated lung metastases." (PMID 33671476, 2021). "As expected, breast cancer cells treated with tamoxifen showed minimal recruitment of Med1 on the EREs of ER-responsive genes as well as reduced levels of acetylated H3 and H4 binding." (PMID 34389732, 2021). "Earlier studies have shown that Med1 is essential for the expression of ER-dependent genes and estrogen mediated breast cancer growth." (PMID 34389732, 2021). "Specifically, Her2+ breast cancer cells were targeted with an RNA nanoparticle carrying two siRNAs for MED1 (a well-known transcriptional co-activator of Her2) and an RNA aptamer targeting Her2." (PMID 33671476, 2021). "Among them, MED1 is overexpressed in more than 50% of human breast cancer cases, and it is also known as HER-2." (PMID 34612778, 2021). "We also noted that breast cancer patients with estrogen receptor positive breast cancer exhibited better overall survival with higher miR-205, low Med1 and low leptin expression levels." (PMID 34389732, 2021). "Combined treatment with leptin and EGFR inhibitor, AG1478, inhibited leptin-induced Med1 phosphorylation in comparison to breast cancer cells treated with leptin alone." (PMID 34389732, 2021). "Together, these data indicate a key role for MED1 overexpression in promoting MMTV-HER2 tumor onset and growth, and demonstrate the clinical relevance of our newly established MMTV-HER2/MMTV-MED1 mammary tumor model." (PMID 33691110, 2021). "To directly examine the effect of MED1 overexpression on the colonization phase of mammary tumor metastasis, we injected tumor cells into nude mice through the tail vein." (PMID 33691110, 2021). "ARGLU1 acts in cooperation with MED1 (Mediator Complex Subunit 1) and is required for estrogen-dependent gene transcription and breast cancer cell growth." (PMID 32884031, 2020). "In breast cancer, MED1 and MED4 expression was significantly reduced in tumors, while MED14 was increased." (PMID 31695025, 2019). "Strikingly, MED1 expresssion was significantly enhanced in HER2-positive breast cancers, while reduced in the basal-like subtype." (PMID 31695025, 2019).